C1QTNF12 (C1q and TNF related 12)
Description:
Insulin-sensitizing adipocyte-secreted protein (adipokine) that regulates glucose metabolism in liver and adipose tissue. Promotes glucose uptake in adipocytes and suppresses de novo glucose production in hepatocytes via the PI3K-Akt signaling pathway. Administration lead to reduction of blood glucose. Able to attenuate inflammation in fat tissue.
Synonyms: C1QDC2; CTRP12; FAM132A; MGC105127; ADIPOLIN
Tractability: Antibody: UniProt places it where antibodies can reach, with high confidence; UniProt predicts a signal peptide or a membrane-spanning region; its Gene Ontology location is reachable by antibodies, with medium confidence.
Gene: Protein-coding gene on chromosome 1 (1,242,446 to 1,246,722, reverse strand). Ensembl gene ENSG00000184163.
Subcellular location: Secreted (Adipolin fC1QTNF12); Secreted (Adipolin gC1QTNF12)
Subcellular location (Human Protein Atlas): Vesicles; Predicted to be secreted
Gene Ontology:
Molecular function: hormone activity
Biological process: negative regulation of gluconeogenesis; positive regulation of D-glucose import; positive regulation of insulin receptor signaling pathway; regulation of D-glucose import; signal transduction
Cellular component: extracellular region
Genetic constraint (gnomAD): Loss-of-function variants: 39 observed, 28.15 expected, observed/expected ratio (o/e) 1.39, 90% interval 1.07 to 1.79. The synonymous counts are far from expectation, so gnomAD's model fits this gene poorly and the ratio says little. Missense variants: 497 observed, 351.31 expected, observed/expected ratio (o/e) 1.41, 90% interval 1.31 to 1.52. Synonymous variants: 220 observed, 157.15 expected, observed/expected ratio (o/e) 1.4, 90% interval 1.25 to 1.57.
Homologues: Orthologues: chimpanzee C1QTNF12 (98% identical), macaque C1QTNF12 (92% identical), guinea pig C1QTNF12 (74% identical), pig C1QTNF12 (74% identical), rat C1qtnf12 (72% identical), mouse C1qtnf12 (72% identical), tropical clawed frog c1qtnf12 (55% identical), zebrafish c1qtnf12 (51% identical), dog C1QTNF12 (35% identical). Paralogues in human: ERFE (40% identical).
Diseases named in the same sentence as C1QTNF12 in open-access papers:
C1QTNF12 is named in the same sentence as 21 diseases in open-access papers, as found by Europe PMC text mining. Sharing a sentence is not in itself a finding about the gene and the disease. The quoted sentences say what the papers report.
Tinnitus (1 paper, 2023). Tinnitus is an auditory perception that can be described as the experience of sound, in the ear or in the head, in the absence of external acoustic stimulation. "Meanwhile, down-regulated genes between the tinnitus and the control group were Car3, Egr2, Bcl6b, C1qtnf12, Cartpt, LOC108348062, Nr4a3, Gprc5a, LOC103690128, and Angptl6." (PMID 37190538, 2023).
C1QTNF12 also shares sentences with these, for which no sentence is quoted: Obesity (7 papers); coronary artery disease (5); acute myocardial infarction (4); atherosclerosis (4); diabetes (4); metabolic disorders (3); cardiovascular disease (2); dyslipidemia (2); heart failure (2); Insulin resistance (2); type 2 diabetes (2); Arterial stenosis (1); coloboma (1); coronary artery stenosis (1); endothelial dysfunction (1); Hashimoto thyroiditis (1); Hypertension (1); non-alcoholic fatty liver disease (1); polycystic ovarian syndrome (1); uterine serous carcinoma (1).